CCL17 (C-C motif chemokine ligand 17)
Diseases named in the same sentence as CCL17 in open-access papers (continued):
Sharing a sentence is not in itself a finding about the gene and the disease.
brain hemorrhage (2 papers, 2022 to 2025). "Additionally, reduced CCL17 expression itself may also play a role, as this chemokine modulates synaptic transmission in the hippocampus and exerts neuroprotective effects in experimental brain hemorrhage." (PMID 39607395, 2025). "CCL17 depended on CCR4 activation regulating the PI3K/AKT/FOXO1 signaling pathway to reduce neuronal inflammation and apoptosis after brain hemorrhage." (PMID 35800988, 2022).
cardiac hypertrophy (2 papers, 2022 to 2023). "Ccl17-KO ameliorates age-related and Ang II–induced cardiac hypertrophy, fibrosis, and inflammatory response." (PMID 35687056, 2022). "In conclusion, population studies and experiments based on the disease model of age-related and Ang II–induced pathological cardiac hypertrophy have together revealed the destructive effect of CCL17 on cardiac tissue." (PMID 35687056, 2022). "Herein, we report CCL17’s tendency to display an age-dependent increase in population studies and potential role as a critical participant in age-related and angiotensin II (Ang II)–induced cardiac hypertrophy and HF." (PMID 35687056, 2022). "Therefore, CCL17 blockade may exert its cardioprotective effect by interrupting inflammatory-cascade amplification, thus further resulting in the alleviation of cardiac hypertrophy and fibrosis." (PMID 35687056, 2022). "However, the role of CCL17 in pathological cardiac hypertrophy is yet to be investigated." (PMID 35687056, 2022). "This mechanistic study revealed that CCL17 recruits Th2 cells through binding to CCR4, thus perturbing T cell subset balance, promoting fibrotic-factor release (predominantly IL-4 and IL-17), and resulting in cardiac hypertrophy, fibrosis, and subsequent HF." (PMID 35687056, 2022). "Interestingly, we found that CCL17 was difficult to detect in normal myocardial tissue; nonetheless, it exhibited an explosive increase due to the inflammatory cascade in pathological cardiac hypertrophy." (PMID 35687056, 2022).
chronic kidney disease (2 papers, 2021 to 2023). Impairment of the renal function secondary to chronic kidney damage persisting for three or more months. "In our study cohort of 234 chronic kidney disease (CKD) patients and 65 healthy controls, human cytokine array analysis revealed elevated CCL17 expression in CKD that correlated negatively with renal function." (PMID 34943853, 2021).
cognitive decline (2 papers, 2013 to 2021). "CCL17 deficiency resulted in beneficial microglia responses and rescued mice from cognitive decline." (PMID 24330587, 2013).
cutaneous leishmaniasis (2 papers, 2012). Leishmaniasis affecting the skin. "CXCR3 plays a critical role in the host defense against cutaneous leishmaniasis caused by L. major and helps the Th1 response, while CCL17 is associated with diffuse leishmaniasis and late LCL cases." (PMID 23029578, 2012). "In cutaneous leishmaniasis, a number of chemokines were shown to be expressed in Humans, of which CCL2, CCL19 and CCL17." (PMID 22457760, 2012).
diabetes (2 papers, 2022 to 2024). "Using a linear regression model adjusted for confounding factors (sex, body mass index [BMI], hypertension, smoking status, low-density lipoprotein cholesterol [LDL-C], and diabetes mellitus), our results revealed that the serum CCL17 level was significantly associated with age." (PMID 35687056, 2022). "Remarkably, the expression of CCL17 mRNA, a notable M2 marker, was significantly impacted by the IronQ treatment in PBMCs from individuals with diabetes." (PMID 38658734, 2024). "Specifically, genes such as CCL17, CD163, APOE, CYP27A1, and STAB1, some of which are recognized as anti-atherogenic and anti-inflammatory factors in diabetes patients, were identified within this module." (PMID 38658734, 2024).
encephalitis (2 papers, 2016 to 2025). An acute inflammatory process affecting the brain parenchyma. "IL-4 CCL11, CCL17, CCL21), Th17 (IL-17A, GM-CSF), B cell molecules (BAFF, APRIL) and other cytokine/chemokines including IL-21, IL-1b, IL-12p40, CCL2 and IL-12p70 were detected in less than 50% of patients with encephalitis." (PMID 27575749, 2016).
eosinophilic pneumonia (2 papers, 2013 to 2023). An inflammatory lung disorder characterized by an increased number of eosinophils in the lungs. "CCL17 production by BALF cells increases after smoking in acute eosinophilic pneumonia patients, and elevated CCL17 mRNA levels were observed in a murine model of cigarette smoke-induced airway inflammation." (PMID 23705860, 2013).
glioblastoma (2 papers, 2020 to 2022). The most malignant astrocytic tumor (WHO grade IV). "On the other hand, the expression of CCL17 and CCL22 is elevated in a breast cancer tumor, CCL22 expression is increased in colorectal adenocarcinomas, while CCL17 expression is increased in glioblastoma multiforme." (PMID 33182504, 2020). "The CCR4 chemokines were not selected for further analysis as we observed low proportions of non-lymphocyte cell populations expressing the complementary chemokines CCL17 and CCL22 via scRNA-seq and observed no enrichment of CCR4+ T cells in glioblastoma." (PMID 35464424, 2022).
Hepatic fibrosis (2 papers, 2013 to 2025). The presence of excessive fibrous connective tissue in the liver. "In patients with hepatic fibrosis, only chemokine (C-X-C motif) ligand 17 (CCL17) was significantly upregulated (P ≤ 0.05)." (PMID 23661906, 2013). "The diminished expression of TGF-β and CCL17 in Fabp7−/− macrophages may attenuate liver fibrosis by reducing myofibroblast activation and the migration of Th cells into the liver tissue." (PMID 40017805, 2025).
Hypertension (2 papers, 2020 to 2022). The presence of chronic increased pressure in the systemic arterial system. "The 45 active BP patients were divided into different subgroups by sex, with/without hypertension, with/without cerebrovascular disease, with/without mucosal involvement, serum CCL17 levels > or ≤549.0 pg/mL, positive/negative anti-BP180, and positive/negative anti-BP230." (PMID 32399091, 2020).
liver cancer (2 papers, 2023 to 2024). An epithelial or non-epithelial malignant neoplasm that arises from the liver. "Not only CCR4 but also its ligands CCL17 and CCL22 were found to be highly overexpressed in human and mouse liver cancers." (PMID 37081509, 2023). "In addition to CCR4, its ligands CCL17 and CCL22 found to be elevated in liver cancer, which facilitate Tregs cell infiltration to the tumors leading to the suppression of anti-cancer immunity by TGF-β1 production, and further establishment of a favorable microenvironment for tumor growth." (PMID 37081509, 2023).
lung adenocarcinoma (2 papers, 2020 to 2022). A carcinoma that arises from the lung and is characterized by the presence of malignant glandular epithelial cells. "To further verify the effect of CCL17-induced immune cells on lung adenocarcinoma cell function, we examined the cytotoxic effect of immune cells passing through transwell plates." (PMID 35321241, 2022). "The specific lysis of CCR4-positive cells in the lower chamber of treatment group A (100 ng/ml CCL17) on HLA-A2-positive lung adenocarcinoma H1993 cells was significantly stronger than that of treatment group B (without CCL17), and the difference was significant (p < 0.05)." (PMID 35321241, 2022).
malaria (2 papers, 2016 to 2025). Malaria is a serious and sometimes fatal disease caused by a parasite that commonly infects a certain type of mosquito which feeds on humans. "Notably of the chemokines and cytokines we measured, CCL17 [“thymus and activation related chemokine” (TARC)] and CCL22 [“macrophage derived chemokine” (MDC)] are the only two that are low in malaria." (PMID 27385484, 2016). "The precise meaning of the lower levels of CCL17 and CCL22 in malaria is currently unknown, but it does underscore the complexity of simply analyzing plasma chemokines as markers of mononuclear phagocyte activation status." (PMID 27385484, 2016).
metastatic tumors (2 papers, 2015 to 2023). "Quantitative RT-PCR further confirmed that ICAM-1 deficiency significantly upregulated mRNA levels of IL-10, TGF-β, chemokine (C–C motif) ligand 17 (CCL17), CCL22 (M2-specific cytokines or chemokines) in hepatic metastatic tumors." (PMID 26068788, 2015). "Furthermore, we noted that CCL17 was significantly upregulated in de novo metastatic tumors compared to non-metastatic tumors." (PMID 37686617, 2023).
parasitemia (2 papers, 2021). "Serum levels of IL-6, IL-27, CCL3, CCL5, CXCL10, CCL11, and CCL17 in patients with different parasitic infection profiles living in the rural community of Brejo do Amparo, Januária, Minas Gerais, Brazil." (PMID 33777015, 2021).
Peritoneal Fibrosis (2 papers, 2022 to 2024). Disorder characterized by a wide range of structural changes in PERITONEUM, resulting from fibrogenic or inflammatory processes. "In a mouse model of peritoneal fibrosis induced by sodium hypochlorite exposure, a notable rise in the expression levels of chemokines CCL17 and CCL22 was observed in peritoneal macrophages two days after the injury." (PMID 39749340, 2024). "In the CG-induced mouse model of peritoneal fibrosis, there was an accumulation of CD11bintF4/80int inflammatory macrophages (InfMφs), while injection of anti-CCL17 antibodies significantly reduced InfMφs, myofibroblasts, and peritoneal fibrosis in mice." (PMID 39749340, 2024).
pituitary neoplasms (2 papers, 2023 to 2024). "Another study reported that increased CCL17 expression was associated with a higher concentration of M2 macrophages in pituitary tumors." (PMID 37958702, 2023). "Once activated, TAMs secrete CCL17, a chemokine that further fuels the invasive and metastatic potential of pituitary tumors, which engages the CCL17/C-C chemokine receptor type 4 (CCR4)/mTORC1 axis, thereby enhancing the tumor’s capacity for invasion and metastasis." (PMID 39456135, 2024).
plaque psoriasis (2 papers, 2017 to 2024). "We confirmed that there were more CCL17 expressing cells in plaque psoriasis than in normal skin using immunohistochemistry." (PMID 29066845, 2017).
renal carcinoma (2 papers, 2021 to 2022). A carcinoma arising from the epithelium of the renal parenchyma or the renal pelvis. "The levels of CCL17 and CCL22 are also changed in renal cancer tissue, and the CCL17/CCL22 ratio in plasma is associated with poor prognosis." (PMID 36555280, 2022).
rheumatoid arthritis (2 papers, 2019 to 2025). A chronic, systemic autoimmune disorder characterized by inflammation in the synovial membranes and articular surfaces. "This new GM-CSF → CCL17 pathway appears to be active in rheumatoid arthritis patients since circulating CCL17 levels are dramatically reduced upon anti-GM-CSF receptor monoclonal antibody therapy." (PMID 31552022, 2019).
Skin rash (2 papers, 2021 to 2024). A red eruption of the skin. "CTCL shares many clinical characteristics with AD, such as a skin rash with severe pruritus and increased serum CCL17, LDH, and IgE levels, making it difficult to distinguish between these diseases." (PMID 33670758, 2021). "We have previously reproduced abacavir-induced skin rash using B*57:01-Tg and obtained findings regarding cutaneous manifestations such as rash, infiltration of CD8+ T cells into skin tissues, and elevated serum CCL17 levels." (PMID 38525129, 2024).
Stevens-Johnson syndrome (2 papers, 2021 to 2024). Stevens-Johnson syndrome is a limited form of toxic epidermal necrolysis characterized by destruction and detachment of the skin epithelium and mucous membranes involving less than 10% of the body surface area. "Ogawa’s study revealed a significant increase in serum thymus and activation-regulated chemokine (TARC/CCL17) levels among patients with DRESS compared to those with morbilliform drug eruption and Stevens-Johnson syndrome/Toxic epidermal necrolysis (SJS/TEN)." (PMID 39737180, 2024).
urothelial carcinoma (2 papers, 2022 to 2024). A malignant neoplasm derived from the transitional epithelium of the urinary tract (urinary bladder, ureter, urethra, or renal pelvis). "Our previous studies showed that regulatory T cell recruitment in canine urothelial carcinoma is caused by BRAFV595E mutation-driven CCL17/CCR4 pathway." (PMID 35027594, 2022). "For instance, CCL17 was reported to bind the CCR4 receptor to trigger the migration of Tregs toward canine urothelial carcinoma." (PMID 39046599, 2024).
vasculitis (2 papers, 2015 to 2020). "So the plasma levels of MIG/CXCL9 and TARC/CCL17 can reflect the numbers of activated Th1 and Th2 cells in vasculitis sites in KD patients." (PMID 26337791, 2015). "Since Th1 and Th2 cells can be induced by MIG/CXCL9 and TARC/CCL17 and migrate to vasculitis sites in KD, the levels of activated Th1 and Th2 cells should have an appropriate ratio and play a well-balanced role." (PMID 26337791, 2015). "When inflammation occurs, MIG/CXCL9 and TARC/CCL17 can stimulate Th1 and Th2 cells secreting cytokines to regulate the immunoreaction during the development of vasculitis in KD, and so plasma MIG/CXCL9 levels increase with the development of a serious inflammation." (PMID 26337791, 2015). "However, when vasculitis develops into CAL, plasma MIG/CXCL9 levels could be negatively feedback regulated while TARC/CCL17 increase persistently." (PMID 26337791, 2015).
acute disseminated encephalomyelitis (1 paper, 2022). Acute disseminated encephalomyelitis (ADEM) is a demyelinating disorder of the central nervous system. "Unlike MS, elevated neutrophil chemokines (CXCL7) and Th2 cell chemokines (CCL1, CCL22, and CCL17) were also found in the CSF of acute disseminated encephalomyelitis (ADEM), another inflammatory demyelinating disease, helping to differentiate ADEM from MS." (PMID 35837284, 2022).
Aden (1 paper, 2021). "CCL17 and CCL22 within tumors are known to be associated with an increased population of Foxp3+ Tregs; thus, the high expression of these 2 chemokines may contribute to the infiltration of Tregs into patients with Aden, thereby making the tumor microenvironment more immune suppressive." (PMID 34459571, 2021).
allergic bronchopulmonary aspergillosis (1 paper, 2013). Allergic bronchopulmonary aspergillosis (ABPA) is a rare immunologic pulmonary disorder caused by hypersensitivity to Aspergillus fumigatus, clinically manifesting with poorly controlled asthma and recurrent pulmonary infiltrates. "Moreover, elevated serum CCL17 levels have been proposed as a biomarker of allergic bronchopulmonary aspergillosis." (PMID 24063011, 2013).
allergic conjunctivitis (1 paper, 2023). "In 2020, Shoji demonstrated that tear levels of CCL17/TARC, CCL24/eotaxin-2, and IL-16 in VKC and AKC patients were significantly higher than in patients with other allergic conjunctivitis, like SAC and PAC (p < 0.01)." (PMID 37658939, 2023).
arteriosclerosis (1 paper, 2025). A vascular disorder characterized by thickening and hardening of the walls of the arteries. "Studies have demonstrated that inflammatory mediators such as fractalkine/CX3CL1, CCL8, M-CSF, HGF, E-selectin, PI3/elafin, CCL17, and IL-16 are significantly elevated in patients with AD, contributing to the progression of arteriosclerosis." (PMID 40757030, 2025).
Atherosclerotic lesion (1 paper, 2025). A lesion associated with atherosclerosis, a multifactorial and multipart progressive disease manifested by the focal development within the arterial wall of lesions, that ranges from the development of a fatty streak, plaque progression, and plaque disruption. "Our data show that interactions between CCR4 and CCL17/CCL22 may promote Treg-skewed responses in lymphoid tissues and atherosclerotic lesions." (PMID 40608058, 2025).
atopic asthma (1 paper, 2016). An asthma that is characterized by symptoms that are triggered by an allergic reaction caused by inhaled allergens such as dust mite allergen, pet dander, pollen and mold. "In patients suffering from atopic asthma, it was shown that after a challenge with HDM, the concentrations of CCL17 were also increased in the BALF." (PMID 26003185, 2016).
basal cell carcinoma (1 paper, 2021). A carcinoma involving the basal cells. "For instance, recently, Omland and colleagues reported that CCL17 secreted from resident CAFs within cutaneous basal cell carcinoma TME increases tumor progression and amplifies immune suppression." (PMID 34680267, 2021).
brain injury (1 paper, 2025). Acute and chronic (see also brain INJURIES, CHRONIC) injuries to the brain, including the cerebral hemispheres, CEREBELLUM, and brain STEM. "These multiple sources of CCL17 reflect the complex interplay between central and peripheral immune responses following brain injury." (PMID 39996481, 2025).
cervical cancer (1 paper, 2025). A primary or metastatic malignant neoplasm involving the cervix. "In cervical cancer, low expression of CCL17 is associated with favorable prognosis." (PMID 40517358, 2025).
Chagas disease (1 paper, 2019). A parasitic infection caused by Trypanosoma cruzi. "Remarkably, IL-12p40 and CCL17 (TARC), molecules related to T cells response, had reduced levels in patients with severe form of Chagas disease." (PMID 31379862, 2019).
chronic asthma (1 paper, 2018). An asthma that is characterized by the development of persistent airway inflammation and recurrent attacks of breathlessness and wheezing, which vary in severity and frequency. "Nevertheless, our data demonstrated a previously unappreciated mechanism that in response to allergen challenge, lung cDC1s attract eosinophils directly through secreting CCL17 and CCL22 during the memory stage in chronic asthma." (PMID 30250029, 2018).
chronic lung disease (1 paper, 2021). According to the definitions of the American and British Thoracic Societies, including pulmonary functional tests, X-rays, and CT scans for items such as fibrosis, bronchiectasis, bullae, emphysema, nodular or lymphomatous abnormalities. "We analyzed the expression of selected genes associated with AM plasticity (Ccl22, Ccl17, Mmp12, and Arg1) and inflammation in chronic lung diseases (Il1a and Il1b)." (PMID 34764283, 2021).
clear cell renal cell carcinoma (1 paper, 2017). "The aim of this study was to investigate prognostic values of CCL17 expression in patients with clear cell renal cell carcinoma (ccRCC)." (PMID 28178948, 2017).
dyslipidaemia (1 paper, 2018). "Here we observed a strong correlation between free cholesterol within VLDL-2 and both CCL-17 and IL-7 highlighting a potential interaction between inflammation and dyslipidaemia." (PMID 30451923, 2018).
endotoxemia (1 paper, 2022). "Flow cytometry analysis showed a higher number of F4/80+Ly6GhiLy6Chi cells that highly expressed M2-like macrophage markers (Ym1, Arg, CCL17) in the peritoneal cavity of the F-652-treated endotoxemia mice." (PMID 36123595, 2022).
enteritis (1 paper, 2024). Inflammation of the small intestine. "Both Que and RU.521 could significantly reduce the protein levels of CXCL10 and TNF-α while increasing the protein levels of IL10 and CCL17 following the induction of enteritis." (PMID 38774206, 2024). "Following DSS-induced enteritis, there was a significant increase in the protein levels of CXCL10 and TNF-α, coupled with a notable decrease in IL10 and CCL17." (PMID 38774206, 2024).
Fulminant hepatitis (1 paper, 2021). Acute hepatitis complicated by acute liver failure with hepatic encephalopathy occurring less than 8 weeks after the onset of jaundice. "Moreover, CCL17 was also reported to be a MDSC-attracting chemokine induced by IL-25 in D-galactose (D-Gal)/LPS-induced fulminant hepatitis (FH) mice." (PMID 34869447, 2021).
gastritis (1 paper, 2010). Inflammation of the stomach. "H. pylori-infected individuals with uncomplicated gastritis showed a significantly elevated expression of mRNA for both M1 (iNOS, 8-fold; CXCL11, 20-fold) and M2 markers (CCL17, 30-fold; CCL18, 70-fold, CD206, 2-fold) compared to uninfected volunteers." (PMID 21124899, 2010).